SCARF1 (scavenger receptor class F member 1)
Description:
Mediates the binding and degradation of acetylated low density lipoprotein (Ac-LDL). Mediates heterophilic interactions, suggesting a function as adhesion protein. Plays a role in the regulation of neurite-like outgrowth (By similarity).
Synonyms: SREC-I; KIAA0149; SREC; SREC1
Tractability: Antibody: its Gene Ontology location is reachable by antibodies, with high confidence; UniProt predicts a signal peptide or a membrane-spanning region.
Gene: Protein-coding gene on chromosome 17 (1,633,851 to 1,645,753, reverse strand). Ensembl gene ENSG00000074660.
Subcellular location: Membrane
Subcellular location (Human Protein Atlas): Golgi apparatus
Pathways (Reactome):
Vesicle-mediated transport: Scavenging by Class F Receptors
Gene Ontology:
Molecular function: low-density lipoprotein particle binding; protein binding; scavenger receptor activity; transmembrane signaling receptor activity
Biological process: cholesterol catabolic process; dendrite development; heterophilic cell-cell adhesion; neuron remodeling; positive regulation of axon regeneration; positive regulation of neuron projection development; receptor-mediated endocytosis
Cellular component: membrane; endocytic vesicle membrane; plasma membrane
Genetic constraint (gnomAD): Loss-of-function variants: 52 observed, 62.83 expected, observed/expected ratio (o/e) 0.83, 90% interval 0.66 to 1.04. The upper end of that interval is the gene's LOEUF score, 1.04, which puts it in group 4 of 6, group 1 being the genes least tolerant of losing a copy. Missense variants: 1,098 observed, 1,035.6 expected, observed/expected ratio (o/e) 1.06, 90% interval 1.01 to 1.11. Synonymous variants: 495 observed, 438.04 expected, observed/expected ratio (o/e) 1.13, 90% interval 1.05 to 1.22.
Homologues: Orthologues: chimpanzee SCARF1 (99% identical), macaque SCARF1 (93% identical), rabbit SCARF1 (79% identical), dog SCARF1 (78% identical), pig SCARF1 (78% identical), mouse Scarf1 (71% identical), rat Scarf1 (71% identical), guinea pig SCARF1 (60% identical), tropical clawed frog scarf1 (45% identical), zebrafish scarf1 (43% identical). Paralogues in human: SCARF2 (37% identical), CRB2 (20% identical), CRB3 (2% identical).